TERT (telomerase reverse transcriptase)
Diseases named in the same sentence as TERT in open-access papers (continued):
Sharing a sentence is not in itself a finding about the gene and the disease.
glioma (continued). "Current prognostic tools for glioma primarily rely on factors such as WHO grade, IDH mutations, 1p/19q codeletion, MGMT promoter methylation, TERT promoter mutations and EGFR amplification." (PMID 39355251, 2024). "Previous studies have consistently shown the effectiveness of the nomogram in accurately predicting glioma TERT classification." (PMID 38798094, 2024). "In particular, IDH1 and TERT have a significant prognostic impact on gliomas to the extent that they can be used as clear criteria for CNS tumor classification." (PMID 38877400, 2024). "For lower-grade gliomas, the coexistence of IDH and TERT mutations was associated with a survival advantage, corroborating existing literature." (PMID 38982347, 2024). "In low-grade gliomas (Grades 2 and 3), TERT-p mutant patients have a better prognosis than wildtype patients, but in GBs (Grade 4), TERT-p mutations are associated with poor outcomes." (PMID 38893240, 2024). "When we exclude patients carried TERT promoter mutations, a significant difference was found between high and low level of RTEL1 mRNA groups in 238 glioma patients (p < 0.05)." (PMID 38532312, 2024). "We observed that high expression of RTEL1 is positively correlated with telomere length in glioma tissue, and serve as a poor prognostic factor in TERT wild-type patients." (PMID 38532312, 2024). "In our study, patients with high-grade glioma had the following mutational frequencies according to the tumor variety: glioblastoma (GBwt-IDH), in which mutations in the TERT promoter (13/22 Patients), and EGFR promoter (5/22 Patients)." (PMID 39767683, 2024). "Currently, molecular markers for adult glioma classification and prognosis include IDH1/2 mutations, homozygous deletion of CDKN2A and/or CDKN2B, EGFR amplification, and TERT promoter mutation." (PMID 37214395, 2023). "Necrotic volume percentages of core (CNV), age, choline‐to‐creatine ratio, lactate, and a radiomics score were found to be significantly higher in TERT‐mutant than in TERT wild‐type high‐grade gliomas in a study using conventional MRI together with MRS." (PMID 36912262, 2023). "Important examples of molecular alterations in adult-type gliomas include EGFR amplification, TERT promoter mutation, and +7/-10 chromosomal copy number alterations in high-grade astrocytic tumors with IDH wild type." (PMID 37626776, 2023). "Italian researchers designed a glioma panel spanning 13 genes and a p-TERT region with the possibility of detecting 1p/19q-codeletion." (PMID 37908227, 2023). "Telomerase is strictly regulated in normal somatic cells, but most tumor cells, including gliomas, maintain telomere length by abnormally upregulating TERT expression." (PMID 37570630, 2023). "The gain of chromosome 7 / loss of chromosome 10 and TERT promoter mutation are frequently observed in glioblastoma multiforme (GBM) genetic alterations and have been linked with highly aggressive glioma." (PMID 37537630, 2023). "Contrast‐enhanced T1, FLAIR, and ADC maps played an important role in detecting IDH‐mutant TERT promoter‐mutant gliomas." (PMID 36176070, 2023). "In terms of well-known molecular markers, IDH mutation, 1p/19q codeletion, MGMT promotor methylation, wild-type TERT promoter, and ATRX mutation glioma samples correlated with lower infiltration of reactive astrocytes." (PMID 37416308, 2023). "TERT promoter mutations and loss of function ATRX mutations are usually mutually exclusive, as has been observed in gliomas." (PMID 37629169, 2023).
glioma (continued). "Using the supervised DNA methylation classification, transcriptional subtype, MGMT promoter status and TERT promoter status to color the adult gliomas from TCGA-LGG and TCGA-GBM also revealed distinct patterns across the adult glioma landscape." (PMID 36711972, 2023). "The panel can be used for profiling patients with glioma as it includes most of the essential glioma SNVs, missing only p-TERT DNA sequence alterations." (PMID 37908227, 2023). "CeGaT, missing only p-TERT and H3-3A for full glioma marker gene analysis; additionally, the possibility of 1p/19q-codeletion detection is not clear." (PMID 37908227, 2023). "The autoML algorithm searched through a series of modeling pipelines combining different data feature reduction methods and models to find the best pipeline for detecting IDH‐mut TERT promoter‐mut gliomas." (PMID 36176070, 2023). "We previously demonstrated the utility of GSH and lactate in the 1H-MRS spectrum, as well as HP lactate production detected by 13C-MRS, as biomarkers for TERT-positive glioma and TERT modulation by TERT or GABP silencing." (PMID 36997627, 2023). "Among gliomas with FGFR3::TACC3 fusion, age, TERT promoter mutation, pathological features, DNA-methylation profiling and fusion subtype are of interest to determine patients’ risk." (PMID 36647073, 2023). "We first extracted quantitative features using radiomic analysis and selected those most relevant to IDH‐mutant TERT promoter‐mutant gliomas in a data‐driven approach." (PMID 36176070, 2023). "Of note, TERT mutations and ATRX mutations are mutually exclusive in gliomas, and the exact mechanism of how ATRX mutations, in particular, induce ALT in gliomas is still under investigation." (PMID 37626776, 2023). "The “alternative lengthening of telomeres” (ALT), which depends on the ATRX/DAXX complex, is mutually exclusive with TERT in gliomas." (PMID 38201248, 2023). "Namely, the role of secondary mutations in epigenetically driven glioma has only been superficially defined, with an unclear role of key oncogenic driver genes such as EGFR, PTEN, RB1, NF1, TERT, and CDKN2A on modulating the tumor microenvironment." (PMID 37706202, 2023). "Both panels include important genes for glioma, however, PGDx elioTM plasma for solid tumors is intended for 500+ genes and can detect most of the glioma markers including p-TERT DNA sequence alterations." (PMID 37908227, 2023). "In conclusion, we identified specific radiomic features that detect gliomas with IDH and TERT promoter mutations from multi‐modal MRI that consisted of T1c, FLAIR, and ADC maps." (PMID 36176070, 2023). "Illumina (San Diego, United States) sells TruSight Oncology 500/500 ctDNA RUO panel investigating 523 genes in tumor specimen or ctDNA covering all glioma marker SNPs including p-TERT DNA sequence alterations." (PMID 37908227, 2023). "This study attempted to develop a noninvasive method to detect IDH‐mutant TERT promoter‐mutant gliomas using preoperative multimodal MRI." (PMID 36176070, 2023). "Some studies applied radiomics and identified the TERT promotor genotype in gliomas with an accuracy of over 60%." (PMID 37830090, 2023). "According to molecular genetic characteristics, some important glioma subtypes, including IDH mutation, TERT promoter, and 1p/19q codeletion, improve the therapeutic efficacy for glioma." (PMID 36118697, 2022). "In order to investigate the potential of TERT promoter mutation status as a prognostic factor, we compared the overall survival (OS) of TERT-p mutant and wildtype gliomas using E-MTAB-3892 dataset and a GBM cohort from a previous study." (PMID 35495630, 2022).
glioma (continued). "Our study strongly supports using TERT and IDH genotyping in WHO grade II/III gliomas as a reliable and reasonable test that can help clinicians predict patient outcome more precisely than using only conventional histology, or TERT or IDH status alone." (PMID 34558656, 2022). "The investigated ddPCR-based assays enable the detection of diagnostically relevant glioma-associated mutations in the IDH1, IDH2, H3-3A, BRAF, and PRKCA genes, as well as in the TERT promoter." (PMID 35361262, 2022). "DWI metrics can predict glioma grading and IDH mutation noninvasively, but have limited use in detecting TERT mutation and MGMT methylation." (PMID 36471242, 2022). "Patients with wild-type (WT) TERT, IDH, and persevered 1p19q (triple negative) were associated with GBM, and had worse prognosis than triple-positive gliomas, but had a better prognosis than in patients with TERT mutations only." (PMID 34558656, 2022). "In contrast, the TERT and EGFR somatic mutations and CDKN2A/B copy number alterations are significantly depleted in the Chinese glioma cohort (P < 0.05)." (PMID 36350002, 2022). "Therefore, MRI-based radiomics features are reliable for the non-invasive assessment of TERT promoter mutation status in gliomas, and future studies need to explore whether the addition of more imaging modalities and sequences can further improve the predictive performance." (PMID 35807084, 2022). "Together with another group, we were the first to show the usefulness of mutations of TERT promoter (TERTp), when combined with IDH genotype, in the precise prognostication of low-grade gliomas." (PMID 35558510, 2022). "Our data are supporting and extending recent reports on the use of ddPCR assays to detect mutations in glioma tissue samples, including IDH mutations, TERT promoter mutations, H3-3A mutations, and BRAF duplication." (PMID 35361262, 2022). "In grade three gliomas with IDH mutations, several studies have reported that TERT promoter mutations are associated with favorable outcomes." (PMID 36614997, 2022). "Mutations in modifiers such as isocitrate dehydrogenase 1/2 (IDH1/2) and telomerase reverse transcriptase (TERT) lead to global changes in the epigenome, being common companions of glioma pathogenesis." (PMID 35330864, 2022). "Analysis of TERT promoter mutation status and EGFR amplification showed that TERT mutated glioma show increased copies of EGFR using FISH and EPIC without statistical significance (p > 0.05, Student’s t-test)." (PMID 35453544, 2022). "The detection and reporting of alterations such as IDH1/2 mutation, 1p/19q co-deletion, EGFR amplification, TERT-promoter mutation, and CDKN2A homozygous loss in the diagnosis of infiltrating glioma has become standard practice in clinical neuropathology." (PMID 36397144, 2022). "TERT promoter mutations were shown to have inverse prognostic effects in IDH-mut and IDH-WT WHO grade II/III gliomas." (PMID 34558656, 2022). "A further study found that the genetic risk for acquiring glioma was associated with EGFR in males, and to TERT instead in females, indicating biologically relevant sex differences in gliomagenesis." (PMID 35159938, 2022). "Most driver genes were only found in single cancer types and represented key disease-specific drivers such as EGFR and TERT in glioma, MYC in BNHL, and APC in colorectal cancer." (PMID 35947558, 2022). "This indicated that CCN4 was closely related to IDHwt and TERT promoter, which affected the prognosis of glioma." (PMID 36589241, 2022).
glioma (continued). "Several critical prognostic factors of glioma, including IDH mutation, 1p/19q codeletion, and TERT promoter mutation, were found to be tightly correlated with the expression pattern of CRGs and the CRGRS." (PMID 36267281, 2022). "Next, we performed an integrated analysis of EGFR amplification and molecular glioma hallmarks: IDH1/2 mutations, TERT promoter mutations, MGMT promoter methylation, and LOH 1p/19q." (PMID 35453544, 2022). "According to the WHO criterion, glioma can be classified by the codeletion statue of 1p/19q, the mutation status of IDH, and the promoter of TERT." (PMID 35646664, 2022). "Changes in TERT and IDH are not only associated with specific histological glioma subgroups, but also are associated with a variable prognosis." (PMID 34558656, 2022). "Standard glioma biomarker data collected into BRAIN includes 1p19q codeletion, IDH mutation, MGMT methylation, ATRX mutation and TERT promotor mutation with a free text field to capture other biomarkers of interest." (PMID 35655179, 2022). "Our results showed that constructed multiparametric model from MRI radiomics features can identify phenotype status of IDH, MGMT and TERT in preoperative MRI scans of patients with glioma." (PMID 35931979, 2022). "To the best of our knowledge, we firstly predicted molecular groups of gliomas based on the status of IDH mutation, 1p/19q codeletion, and TERT promoter mutation using multiparametric MRI radiomics." (PMID 34312469, 2021). "Among the 20,497 genes analyzed, 3,265 genes were upregulated in TERTmut gliomas, and 1,682 genes showed increased expression in TERT wild-type ones (adjusted p < 0.01)." (PMID 33996815, 2021). "The present study confirms the upregulation of TERT in primary glioblastomas while all GABP proteins rise with the malignancy of the gliomas." (PMID 34194624, 2021). "Grade II and III IDH wild-type glioma in adults behave equivalent to GBM, especially when they have TERT promoter mutation, EGFR amplification, and/or chromosome 7 gain and chromosome 10 loss." (PMID 34715891, 2021). "Since gliomas show distinct molecular hallmarks, we next performed an integrated analysis of PD-L1 TPS and molecular genetic status: IDH mutation, TERT promoter mutation, MGMT promoter methylation and loss of heterozygosity of 1p and 19q (LOH 1p/19q)." (PMID 33963441, 2021). "In this study, we investigated the mRNA expression and association between TERT and GABPA/B isoforms in tumor samples of different glioma grades." (PMID 34194624, 2021). "In line with the bioinformatics findings, the profiles of infiltrated immune cells differed between TERTmut and TERT wild-type gliomas." (PMID 33996815, 2021). "Gliomas can be classified into five molecular groups based on the status of IDH mutation, 1p/19q codeletion, and TERT promoter mutation, whereas they need to be obtained by biopsy or surgery." (PMID 34312469, 2021). "That the effect of the TERT promoter mutation on patient survival can be modulated by IDH mutation and other genetic events in glioma patients has been suggested in prior studies." (PMID 34085407, 2021). "Among the 822 immune genes, the expression levels of 361 genes were upregulated in TERTmut gliomas and 91 genes in TERT wild-type cells (t-test, p < 0.05)." (PMID 33996815, 2021). "While brain cortical samples were used as the normal reference for gliomas, the highest TERT expression among normal brain tissue subtypes, was in basal ganglia structures." (PMID 33924498, 2021). "It was revealed that telomerase reverse transcriptase (TERT) and EZH2 jointly stimulated PCG-1α resulting in the secretion of fatty acid synthase (FASN) in glioma having (TERT) promoter mutations." (PMID 34745848, 2021).
glioma (continued). "Molecular alterations, such as IDH 1/2 mutations, ATRX mutations, 1p/19q codeletion, TERT promoter mutations, and MGMT promoter methylation have also been highly studied for glioma molecular classification and prognostication." (PMID 34277415, 2021). "TERT promoter mutation is commonly present in ODGs (78%) and IDH-wildtype GBMs (83%) and is considered as a potential grouping marker in glioma." (PMID 33981597, 2021). "TERT and ALT are associated with unique magnetic resonance spectroscopy-detectable metabolic signatures in genetically engineered and patient-derived glioma models." (PMID 34445646, 2021). "Mutations in the TERT promoter can improve gene transcription, leading to increased TERT mRNA levels, which predict a poor prognosis in glioma patients." (PMID 34814870, 2021). "Similar to our findings, few studies have used ddPCR to identify the prevalence of TERT promoter mutation in blood and urinary cell-free tumor DNA and FFPE specimens to monitor melanoma, urothelial cancer, glioma, and thyroid." (PMID 33776938, 2021). "Reports have pointed out that TERT was able to enhance stemness of glioma cells by modulation of epidermal growth factor receptor (EGFR) expression." (PMID 33869033, 2021). "Early evidence has confirmed that gliomas with IDH mutation and 1p/19q codeletion have better survival, whereas glioblastoma with telomerase reverse transcriptase (TERT) promoter mutation have worse survival." (PMID 34312469, 2021). "Our study aims to explore the correlation between tumor grade, the status of IDH, MGMT, TERT and tumor perfusion indicators in glioma patients." (PMID 34814870, 2021). "TERT mutation is preferentially present in glioblastoma and IDH-wt gliomas and is associated with poor prognosis." (PMID 33996815, 2021). "Pattern A, which includes breast (overall, ER-positive, and ER-negative), colorectal, glioma, ovarian, and prostate cancer, displayed one sharp genome-wide significant signal in a narrow region (~30 kb) overlapping the TERT gene (chr5: 1,253,282–1,295,178 bp)." (PMID 34355204, 2021). "First, we found that glioblastomas are more prone to TERT mutations than grade II and grade III gliomas as well as gliomas with IDHwt or 1p19q codeletion." (PMID 33996815, 2021). "Notable genes with SNV-associated increased expression include TERT, COPS3, POLE2 and HDAC2—involving multiple cancer types—MYC, BCL2, PIM1 and IGLL5—involving lymphomas—and CYHR1—involving pediatric low-grade gliomas." (PMID 33554123, 2021). "Several candidate SNP studies have been conducted in East Asian populations, which have found novel association loci for glioma as well as validated those discovered in European-ancestry populations, including loci in TERC, TERT, EGFR, and PHLDB1." (PMID 34817716, 2021). "HIF1A and HIF2A significantly increased TERT promoter activity in renal cell carcinoma cell lines, while HIF2A alone inhibited TERT promoter activity in glioma cell lines." (PMID 33802026, 2021). "In Reference the authors study glioma groups based on 1p/19q status and IDH and telomerase reverse transcriptase (TERT) promoter mutations in tumors." (PMID 34277415, 2021). "The 25th percentile of FA yielded the highest prediction efficiency for glioma grade, IDH mutation, and TERT promoter mutation, while the 75th percentile of MD gave the best prediction of 1p19q codeletion." (PMID 33777772, 2021). "To date, three pilot studies applied radiomics to discriminate TERT promotor genotype in gliomas with an accuracy of around 80%47–49." (PMID 34312469, 2021).